ABO (ABO, alpha 1-3-N-acetylgalactosaminyltransferase and alpha 1-3-galactosyltransferase)
Diseases named in the same sentence as ABO in open-access papers (continued):
Sharing a sentence is not in itself a finding about the gene and the disease.
COVID-19 (continued). "While RALGDS was mapped, its contributory cis-eQTLs were mapped around ABO, which has been suggested to mediate COVID-19 pathogenesis via glycosylation of downstream targets and colocalized in others’ studies, underscoring the complexity of mapping eQTLs." (PMID 37640912, 2023). "In lung, the total expression of ABO and GBAP1 had MR evidence with high colocalization (a posterior probability >0.8) for COVID-19 outcomes (all three COVID-19 outcomes with ABO and reported infection with GBAP1)." (PMID 37794074, 2023). "This study explores the role of genetic variations in blood group antigens, particularly ABO and RhD, in shaping mortality rates among critically ill COVID-19 patients in the southern region of Saudi Arabia." (PMID 38249239, 2023). "Two of the loci described herein—the ABO cluster that associates with CDTA and the PA locus closest to the gene NFKBIZ—have been implicated with COVID-19 severity." (PMID 36653354, 2023). "Our findings are consistent with previous genetic studies showing ABO gene is associated with severe COVID-19 and SARS-CoV-2 infection, possibly by regulating thrombosis, as ABO gene is responsible for post-translational glycosylation of coagulation factors." (PMID 37085521, 2023). "Similar with findings from CPASSOC, we found shared genes between COVID-19 and cancers that are related to hematologic systems (ABO), immune function (MUC1, PLEKHM1), and cell proliferation (KANSL1-AS1)." (PMID 37636041, 2023). "Several studies have identified numerous genetic variants correlated with COVID-19 severity, including ACE2, ABO, CD26, IFITM3, HLA, TLR7, and TMPRSS2." (PMID 38138892, 2023). "Regarding the risk variant of the ABO locus, we observed a risk of rapid deterioration of CXR findings in patients with COVID-19 in the AB blood group." (PMID 38086863, 2023). "We observed that 2 SNPs mapped in the ABO gene (rs579459 Chr9:136154168 and rs495828 Chr9:136154867) showed consistent signals across varied COVID-19 severities, which implied the value of the ABO gene for jointly influencing CHD and COVID-19 (P < 5 × 10–4)." (PMID 37964352, 2023). "Our objective was to estimate the incidence of COVID-19 and the ABO blood Groups in the mass-gathering events (MGEs) during the Falles Festival in Borriana (Spain) from 6–10 March 2020." (PMID 36810454, 2023). "Low ABO antibody levels have been found in COVID-19 cases compared with controls, suggesting that ABO antibodies play a role in protecting against the infection." (PMID 36810454, 2023). "Two SNPs (rs579459 and rs495828) in the ABO gene were assumed to be promising putative causal loci, as they showed consistent signals of pleiotropy when assessing CHD and COVID-19 of the three severity types." (PMID 37964352, 2023). "Two genes were located at pleiotropic loci identified in cross-trait meta-analysis, including ABO (enriched in whole blood and shared by BC with all three COVID-19 phenotypes) and MSTO2P (enriched in muscle skeletal and pancreas)." (PMID 37636041, 2023). "Our study adds to the growing body of literature around the role of ABO in COVID-19 and findings from our study provide further evidence for several associations that have been reported elsewhere." (PMID 34978705, 2022). "We observed consistently lower serum concentrations of anti-A/anti-B in COVID-19 convalescents than in controls, possibly indicating a protective role of ABO antibodies in infection with SARS-CoV-2." (PMID 35956128, 2022). "The patients with ABO rs657152 AA genotypes revealed significantly higher in dead patients compared to improved individuals; nevertheless, improved COVID-19 patients had CC genotypes." (PMID 36419842, 2022). "The distribution of COVID-19 patients on the ABO and RhD blood group demonstrated that blood group AB was more common in the COVID-19 group than the non-COVID-19 group." (PMID 35366803, 2022).
COVID-19 (continued). "In the initial COVID-19 HGI meta-analysis, rs912805253 at the ABO locus showed the strongest susceptibility signal, a signal that was later replicated in 1.05 million research participants from 23andMe." (PMID 35768520, 2022). "There is no doubt that more investigations would be beneficial to understand the role and molecular mechanism of ABO blood groups in COVID-19 fully and help develop novel therapeutic strategies." (PMID 35547235, 2022). "Many follow-up studies have reported ABO and ENPEP as COVID-19 risk genes; however, the evidence for the FUT2 gene is conflicting." (PMID 35736459, 2022). "Among nine genes reported in the international meta-GWAS as genes involved in the onset of COVID-19, the association of FOXP4-AS1, ABO, and IFNAR2 genes was replicated in the Japanese population." (PMID 35264675, 2022). "Based on a threshold of conjFDR <0.05, we identified two loci shared between COVID-19 and T2D: ABO (rs505922, intronic) and NUS1 (rs3924604, intronic)." (PMID 36482905, 2022). "Understanding the role of ABO and its relationship with COVID-19 severe manifestations requires significant effort." (PMID 36419842, 2022). "The COVID-19 Host Genetics Initiative (HG1) report concurred with the association of variants in ABO, SLC6A20, TYK2, DPP9, IFNAR2, and additionally reported a variant in Protein Phosphatase 1 Regulatory Subunit 15A (PPP1R15A) in influencing COVID-19 severity." (PMID 36143338, 2022). "Asthma and COVID-19 share two genome-wide significant genes, including ABO at the 9q34.2 region and OAS2 at the 12q24.13 region." (PMID 35386719, 2022). "The ABO blood type for 462 Japanese COVID-19 patients and 1193 healthy individuals was inferred from the results of genotype imputation." (PMID 35264675, 2022). "Less than 1 month after this latter study, another preprint on possible associations between ABO phenotypes and the risk of either contracting SARS-CoV-2 or the severity of COVID-19 appeared." (PMID 35364749, 2022). "The relationships between ABO blood group antigens and COVID-19 have also been investigated by many researchers." (PMID 35215921, 2022). "ABO, D and P1 blood antigens were determined in 104 blood samples of COVID-19 patients versus 100 control samples using either automated immunohematology analyser or test tube method." (PMID 37092112, 2022). "The genetic and serological evidence of the involvement of ABO blood types and ABO gene allelic relationships with COVID-19 severity gives a unique opportunity to explore the contribution of host genetics to interindividual phenotypic variation." (PMID 36419842, 2022). "To date, this is the third study that investigates the relationship between ABO and COVID-19 in Saudi Arabia." (PMID 34978705, 2022). "We can expect new findings from genome-wide association analyses to explain better the importance of the ABO system in the severity and mortality of patients with COVID-19." (PMID 35547235, 2022). "Once we know the importance of natural antibodies from the ABO system in COVID-19, we should evaluate only the reverse type in terms of protection against viral infection." (PMID 35547235, 2022). "Since the rapid global outbreak of COVID-19, extensive research suggested the ABO blood group system and secretor phenotype in potentially predisposing to infection with SARS-CoV-2." (PMID 35923409, 2022). "In conclusion, our study has demonstrated genetic pleiotropy between T2D and COVID-19 and has identified shared genetic loci (ABO and NUS1) which were validated with a pathway-based analysis." (PMID 36482905, 2022). "In this study, we examined the relationship between ABO blood groups and severity of inflammation, development of complications, and mortality among serologically positive COVID-19 patients." (PMID 35784998, 2022).
COVID-19 (continued). "Consistent with pan- and cis-MR findings, there was evidence of genetic colocalisation between the ABO protein and six out of seven COVID-19 phenotypes, with similar MR estimates when the colocalising SNP was used to perform single-SNP cis-MR." (PMID 34402426, 2021). "Revealing this linkage of ABO and Rh system to the prevalence and mortality of COVID-19 is important in terms of understanding both the pathophysiology of the disease and the convalescent plasma therapy." (PMID 33936883, 2021). "ABO frequencies in the COVID-19-positive subgroup were similar to those of the general population, with only a slightly higher frequency of blood group A and a slightly lower frequency of blood group O, neither of these differences being significant." (PMID 35069504, 2021). "A second possible link between ABO and COVID-19 severity can be found in several studies documenting association of ABO blood groups with thromboembolic disease." (PMID 34972836, 2021). "An association study based on ~50,000 COVID-19 patients further supported the association of genetic variants in ABO, TYK2, DPP9, IFNAR2, SLC6A20 and Protein Phosphatase 1 Regulatory Subunit 15A (PPP1R15A) with the severity of COVID-19." (PMID 34575070, 2021). "In both studies, the ABO blood groups distribution of patients with COVID-19 were compared to that of controls from the local populations." (PMID 33981715, 2021). "With our questionnaire, we were able to recruit over 300 couples with known ABO blood groups including at least one PCR-confirmed case of COVID-19." (PMID 35069504, 2021). "All adult patients who had ABO blood grouping and had been tested positive to COVID-19 by viral RNA polymerase chain reaction testing were enrolled." (PMID 34185186, 2021). "Larger international collaborative studies are warranted to further elucidate the relationship between COVID-19 and ABO blood type, particularly in diverse populations." (PMID 34290882, 2021). "COVID-19 incidence, severity, and mortality rates differ greatly between populations, genders, ABO blood groups, human leukocyte antigen (HLA) genotypes, ethnic groups, and geographic backgrounds." (PMID 34545062, 2021). "We identified common variants in ABO and FOXP4-AS1 and a rare variant in MEF2B to be significantly associated with COVID-19 severity, likely through regulation of the adaptive immunity." (PMID 34465887, 2021). "In conclusion, we observed significant differences in post-COVID-19 complications by ABO, with a higher incidence in B group." (PMID 34639344, 2021). "In response to the first published GWAS of COVID-19, we reported findings that link the ABO signal with a number of clinically actionable targets including coagulation factors (von Willebrand factor [vWF], and Factor VIII [F8]), IL-6, and CD209/DC-SIGN." (PMID 34402426, 2021). "In a more recent genome-wide association study of nearly 2000 SARS-CoV-2 infected individuals, a gene cluster carrying the ABO locus was enriched in patients with COVID-19." (PMID 35178379, 2021). "Therefore, the aim of this study is to ascertain whether the specific ABO blood group is associated with COVID-19 severity and identify allelic variants on the ABO gene that is associated with disease severity in a heterogeneous population sample from the United Arab Emirates (UAE)." (PMID 35096865, 2021). "Our analyses lead to three significant loci predisposing risk to severe COVID-19, including an intronic variant in FOXP4-AS1, a frameshift insertion in ABO, and a Chinese-specific rare intronic variant in MEF2B." (PMID 34465887, 2021). "Meanwhile, interest in investigating the relationship between the ABO blood system and the COVID-19 epidemic is increasing." (PMID 33407977, 2021). "Of the 1031 tests performed, two genes (ABO and OAS1) were significantly associated with COVID-19 related hospitalization (p value <4.85E-5)." (PMID 34315903, 2021).
COVID-19 (continued). "The effects of ABO and Rh blood subgroup differences on the characteristic of the disease in patients with COVID-19 are still a matter of debate." (PMID 33936883, 2021). "Of particular note, we provided pan- and cis-MR evidence with strong genetic colocalisation support for the ABO signal for most COVID-19 phenotypes." (PMID 34402426, 2021). "In terms of biological mechanistic insights, pulmonary endothelial-cells of non-O blood groups are associated with higher VWF protein compared to O-group, accounting for the role that the GWAS ascribed to the ABO-locus in COVID-19." (PMID 32899439, 2020). "For example, a genome-wide association study for COVID-19 with respiratory failure detected a susceptibility locus at a chromosome 3p21.31 gene cluster and a potential involvement of the ABO blood-group system in COVID-19." (PMID 33353565, 2020). "In the ABO gene, the rs657152 SNP showed a weak correlation (r2 = 0.1016, p = 0.5380) with the case fatality rate of COVID-19." (PMID 33396837, 2020). "We aimed to compute the relationship between the ABO blood type, age, sex, and ACE2 gene polymorphism with the susceptibility to COVID-19 in patients from Iran to test if the former can act as a biomarker for the latter." (PMID 33083341, 2020). "Although many non-coding variants in ABO are associated with VWF levels, VTE risk, and COVID-19 severity, the mechanisms underlying these associations remain unclear." (PMID 41311061, 2025). "Blood-group-dependent resistance to symptomatic SARS-CoV-2 infection could be used for the construction of a model based on ABO blood group distribution in a specific population that can predict the incidence of COVID-19 and the spreading of SARS-CoV-2." (PMID 38792740, 2024). "The SNP (rs10490770) located near LZTFL1 suggested direct causality (SNPs → COVID-19 → CHD), and SNPs in ABO (rs579459, rs495828), ILRUN(rs2744961), and CACFD1(rs4962153, rs3094379) may simultaneously influence COVID-19 severity and CHD risks." (PMID 37964352, 2023). "Considering the controversial issues among studies, conducting prospective cohort studies in different geographic areas, including the study of virus variants, genetic background, and potential confounders, is needed to establish the effects of ABO on COVID-19 incidence." (PMID 36810454, 2023). "Recent studies showed that the ABO gene, located in 9q34.2, which determines blood type, may affect COVID-19 disease severity." (PMID 37964352, 2023). "More epidemiologic studies of ABO and COVID-19 incidence could be necessary to resolve current inconsistencies in the potential COVID-19-related risk due to ABO." (PMID 36810454, 2023). "By regulating the circulating levels of several pro-inflammatory and immune adhesion molecules, ABO might contribute to both tumorigenesis and COVID-19 development." (PMID 37636041, 2023). "In the ABO genetic region, only one SNP (rs8176719) showed genome-wide significance in the integrated GWAS, but this SNP is a well-known deletion that determines type O blood, indicating that even Japanese with type O blood are less likely to develop COVID-19." (PMID 35264675, 2022). "The ABO gene potentially plays a role in the pathogenesis of COVID-19 and T2D." (PMID 36482905, 2022). "Other COVID-19-related genes that were implicated in nutritional/metabolic diseases and other comorbid conditions (the ABO gene and others) seem to have no clear relationship with the metabolism and actions of VD." (PMID 36430729, 2022). "In contrast to the severity of COVID-19, there is some evidence that the risk of contracting SARS-CoV-2 may depend on the ABO phenotype." (PMID 35364749, 2022). "While the ABO locus was found to be associated with overall susceptibility to SARS-CoV-2 infection, no such association was noted with the progression to more severe COVID-19." (PMID 35364749, 2022).
COVID-19 (continued). "Moreover, data regarding polymorphisms in 8 genes (HLA, ABO, ACE1, ACE2, APOE, CCR5, TMPRSS2, and IFITM3) were meta-analyzed in relation to the risk of infection and severity of COVID-19." (PMID 35793369, 2022). "However, some associations, such as between ABO and hospitalized COVID-19, or GCNT4 and severe COVID-19, display SNP effects between the exposure and outcome with very large standard errors." (PMID 35239653, 2022). "In the case of COVID-19, cell membrane glycoproteins that act as antigenic determinants of the ABO blood types or the iso-agglutinin ABO system could influence the binding of SARS-CoV-2 to ACE2 receptors." (PMID 35683418, 2022). "The present study investigated genetic variants in the SLC6A20, LZTFL1, CCR9, FYCO1, CXCR6, XCR1, and ABO genes that are potentially related to severe forms of COVID-19 in Amazonian Native American populations, and compared their frequencies with continental populations." (PMID 35455670, 2022). "Although the ABO was found to be statistically significant in the integrated analysis of Japanese GWAS and international meta-analysis, these results suggest that the presence of oral AB antigens is actually important for COVID-19 onset." (PMID 35264675, 2022). "The data drawn in this work are worth examining further in Asia, where the association of host genetic factors and ABO blood type with COVID-19 has not been extensively investigated." (PMID 36292769, 2022). "First, our study is focused solely on ABO and overlooks the possibilities that other confounding factors may affect the response to COVID-19." (PMID 34978705, 2022). "Moreover, combined analysis of ABO and FUT2 genotypes revealed that the presence of oral AB antigens was significantly associated with the onset of COVID-19." (PMID 35264675, 2022). "ABO antibodies may be adsorbed or consumed by viral particles during infection which could also explain why COVID-19 convalescents’ antibody levels were lower than those of controls." (PMID 35956128, 2022). "Moreover, some authors recently suggested different degrees of protection or even therapeutical strategies based on ABO blood groups of COVID-19 patients." (PMID 35364749, 2022). "The distribution of ABO blood types varies throughout populations, and the complexity of distinct characteristics impacting COVID-19 outcome could influence these results." (PMID 36013335, 2022). "Our analytic approach identified several known targets (e.g. ABO, OAS1), but also nominated new proteins such as soluble Fas (colocalisation probability >0.9, p=1 × 10-4), implicating Fas-mediated apoptosis as a potential target for COVID-19 risk." (PMID 34402426, 2021). "The effect of population admixture also likely explains why a study from New York, USA, failed to reveal any significant association between ABO blood types and the risk of COVID-19." (PMID 33499228, 2021). "Finally, two GWAS have identified the loci 3p21.31 (LZTFL1, SLC6A20, CCR9, FYCO1, CXCR6, and XCR1) and 9q34.2 (ABO) with COVID-19 severity." (PMID 33868239, 2021). "However, there is a paucity of comprehensive data demonstrating a relationship between ABO blood groups and distribution, prognosis, mortality, and morbidity of patients with COVID-19 in India." (PMID 34888199, 2021). "Interestingly, in the first GWAS on COVID-19 carried out in a European cohort (Italian and Spanish), one of the two genome-wide significant SNP hits is rs657152 at the ABO gene (the other is rs11385942 at the LZTFL1 gene)." (PMID 34202464, 2021). "In accordance with the anti-ABO hypothesis, in the White COVID-19+ group, O blood group was modestly decreased in comparison to the White COVID-19− group (37% vs. 43%), but in the BAME cohort, the effect was much more pronounced (25% vs. 40%)." (PMID 33499228, 2021).